PDGFRB (platelet derived growth factor receptor beta)
Diseases named in the same sentence as PDGFRB in open-access papers (continued):
Sharing a sentence is not in itself a finding about the gene and the disease.
tumor (continued). "Fibrogenesis in S‐ECM samples is likely due to the presence of an activated cancer‐associated fibroblast (CAF) population in the tumor microenvironment, as indicated by the identification of CAF marker genes as key regulators for S‐ECM, including FAP, ACTA2, PDGFRB, VCAN, and ITGA11." (PMID 36637997, 2023). "OT-I killing assays verified that PDGFRB blockade enhanced tumor apoptosis by CD8+T cells." (PMID 37658364, 2023). "Furthermore, individual specimens obtained from our institutional biobank also verified more than tenfold higher expression of PDGFRβ in HCC tumor tissues than that in healthy liver tissues by immunofluorescence and Western blotting." (PMID 37256321, 2023). "In the four groups of subcutaneous tumor models constructed with empty vector cells, the expression levels of PDGFRβ and p-AKT473 in the Ezetimibe treatment group alone were significantly lower than those in the vehicle control group and the SC79 treatment group alone." (PMID 38027998, 2023). "Additional modifications to the PDGFRB-targeting nanobody may be generated to optimize tumour-specific uptake and retention." (PMID 36139509, 2022). "Therefore, we deem it unlikely that tracers such as VHH1E12 would have a major impact on PDGFRB signalling in the tumour microenvironment." (PMID 36139509, 2022). "In vivo, RGR-mediated binding to PDGFRβ-expressing pericytes might contribute to the enhancement of tumor uptake of RGR-TRAIL." (PMID 35635308, 2022). "In addition, we found that both the PDGFRB-targeting and control nanobodies accumulated in areas of tumour necrosis." (PMID 36139509, 2022). "However, when NSG animals were inoculated with a low density of Δ/Δ Pdgfrb cells, we observed a significant delay in tumor growth resulting in an average of 38 days to reach the experimental end point, compared to 29 days for the PDGFRβ expressing tumors." (PMID 36045346, 2022). "Furthermore, an increased immunopositivity of PDGFRβ in stromal/tumor cells was evident in all recurrent cases during denosumab treatment." (PMID 36091939, 2022). "Besides TGFB1, the platelet-derived growth factor receptor PDGFRB was significantly upregulated in the F(h) ROIs, which agrees with increased CAFs and fibrosis in the corresponding tumor microenvironment." (PMID 36216799, 2022). "Proteomic analysis has revealed more than 150 different proteins in EVs secreted by human serum-derived MSCs (SD-hMSCs), the majority of which support tumor growth, including platelet-derived growth factor receptor β (PDGFRβ), tissue inhibitor of metalloproteinase-1 (TIMP-1) and TIMP-2." (PMID 35842634, 2022). "The tumour stroma of peritoneal metastasis clearly showed PDGFRB expression." (PMID 36139509, 2022). "Similarly, in regions of microvascular proliferation and the leading edge of the tumor, PDGFRB is highly expressed." (PMID 36046049, 2022). "As we detected elevated IL-10 levels in primary tumor cells expressing PDGFRβ, we hypothesized that overexpressed PDGFRβ might additionally fuel STAT3 activity in ALCL." (PMID 36045346, 2022). "Interestingly, the six ALCL patients with upregulated PDGFRB expression also showed a downregulation of IL-19 and an upregulation of IL-10 mRNA levels in tumor cells compared to healthy control cells." (PMID 36045346, 2022). "Tumor-normal and inter-tumor analyses of protein expression data highlighted multiple aberrantly-expressed protein targets in key signaling pathways, including PDGFRB, CDK6, ERBB2, and EGFR whose protein overexpression in HCC tumors are also validated by IHC data from the Human Pathology Atlas." (PMID 35433463, 2022). "Recurrent tumors after denosumab treatment displayed a similar intensity of PDGFRβ immunostaining as it could be observed in the primary biopsies which means, the intensity of PDGFRβ immunostaining in stroma/tumor cells was restored/decreased." (PMID 36091939, 2022).
tumor (continued). "Furthermore, these observations also point towards the complex interplay between PDGFRb as a potential marker of distinct stroma cell populations and at the same time as an active signaling receptor driving tumor progression." (PMID 33661437, 2021). "PDGFRβ expression was markedly elevated in the tumor tissues (vs adjacent normal liver tissue)." (PMID 34686668, 2021). "In many patients with eosinophil-rich neoplasms, a mutation in PDGFRA or PDGFRB is detected." (PMID 34052871, 2021). "The correlation between platelet count and tumor cell PDGFRB warrants further studies." (PMID 33955203, 2021). "PDPN, PDGFRβ, and αSMA behave similarly and all decrease over time in both tumour types, while the newest CAF marker, CD26, stands out as the only marker with intriguing opposite dynamics over time when comparing the two different tumours: increasing in the aggressive 4T1 while decreasing in 4T07." (PMID 34016130, 2021). "However, NT5E+ cells, TNC+ cells, and PDGFRβ+ cells shifted from ASPN− to ASPN+ in the cribriform tumor microenvironment." (PMID 33600062, 2021). "Moreover, while pSTAT3 expression was undetectable in adjacent normal liver tissue, low levels of pSTAT3 expression within/near PDGFRB+ cells were seen in the CCC tumor tissue." (PMID 34686668, 2021). "After validation, we conclude that tumor PDGFRB expression was seen in all histological subtypes." (PMID 33955203, 2021). "Furthermore, double staining of VEGFD and PDGFRB (a biomarker for myofibroma, myofibroblasts and pericytes) demonstrated that tumour cells expressed the two proteins." (PMID 33830670, 2021). "In addition, PDGFRβ is consistently expressed in the tumor microenvironment, where it promotes angiogenesis via the tumor stroma, further contributing to the tumor progression and metastasis." (PMID 34522225, 2021). "After combining all three markers into one multivariable model, high tumor cell PDGFRB (HR = 1.01, 95% confidence interval [CI] = 1.00–1.03; p = 0.005) and high stromal SPARC (HR = 1.05, 95% CI = 1.00–1.11; p = 0.045) remained independently associated with survival." (PMID 33955203, 2021). "The fact that tumor PDGFRB independently predicted overall survival in the primary cohort, but not in the validation cohort, could be related to the differences in the patient populations in these cohorts or due to lack of power." (PMID 33955203, 2021). "It is possible that a high blood platelet count indicates higher tumor cell PDGFRB expression." (PMID 33955203, 2021). "This study suggested that the peptide PDGFR-P1 could be useful for developing novel peptide-based ligands of platelet-derived growth factor receptor beta for tumor monitoring." (PMID 33918836, 2021). "The trained AI model detected PDGFRB‐positive tumor cells in 33 out of 74 patients (45%)." (PMID 33955203, 2021). "PDGFRB is thought to play a role in driving the growth and aggressiveness of multiple tumor types." (PMID 34266873, 2021). "In summary, we found that type A pericytes contribute to tumor-associated PDGFRβ+ stromal cells, however not as the main source." (PMID 34535655, 2021). "Notably, we detected that some cells in tumors generated by Pdgfrβ KO p18−/−;Brca1MGKO cells expressed high levels of E-cad, whereas E-cad-positive cells in tumors generated by Pdgfrβ WT p18−/−;Brca1MGKO tumor cells were rarely observed." (PMID 33478572, 2021). "It was shown that the pericyte coverage and basement membrane support were both remarkably elevated upon Tan IIA treatments, as validated by the increased expression of platelet-derived growth factor receptor β (PDGFRβ) and collagen type IV (Col IV) in the tumor blood vessels, respectively." (PMID 34804370, 2021). "We observed a statistically significant correlation between tumor cell PDGFRB and stromal SPARC expression, whereas high stromal SPARC expression correlated inversely with the expression of mesothelial marker staining (combination of CK5, calretinin, and CK5/6)." (PMID 33955203, 2021).
tumor (continued). "To determine whether Pdgfrβ and Pkcα activity represented therapeutic target in BRCA1-deficient tumors, we treated p18−/−;Brca1MGKO tumor cells with a PDGFR Inh III and PKCα inhibitor, Ro-31-8220." (PMID 33478572, 2021). "By using two different PDGFRB staining and analytical methods, we conclude that high tumor cell PDGFRB expression, measured either as intensity (fluorescence staining) or relative positive area (DAB staining), is associated with shortened survival in MPM patients." (PMID 33955203, 2021). "To summarize, selective and unselective impairment of PDGFRβ kinase function rendered similar effects on the tumor pericyte populations in the ASKA PDGFRβ mutant mice, although in most cases stronger effects were observed upon selective PDGFRβ signaling inhibition." (PMID 31938055, 2020). "The lack of therapeutic benefit of imatinib is counter intuitive, since it inhibits the activity of PDGFRβ as well as other kinases 47, hence one may have expected stronger anti-tumor effect by imatinib treatment." (PMID 31938055, 2020). "We studied cancer cell lines with no or low PDGFRβ expression, and used the ASKA mouse model, which provided an opportunity to elucidate the specific role(s) of PDGFRβ signaling in the host during tumor growth and explore the value of highly selective PDGFRβ kinase inhibitors as anti-cancer drugs." (PMID 31938055, 2020). "Interestingly, we found TSPO expression in CD31-positive endothelial cells, as well as in PDGFRB-positive pericytes attached to the newly forming vasculature within the tumor region." (PMID 31963507, 2020). "Moreover, PDGFRβ expression has been shown as a unique feature of tumor cells characterized by a mesenchymal/stem and poorly differentiated phenotype, and it correlates with aggressiveness and resistance to therapy in multiple tumor types." (PMID 32892748, 2020). "Specifically, FGF2 is the main member of the FGF family implicated in cancer development and drug resistance, and PDGFD and its receptor (PDGFRB) have been recently defined as key drivers of tumor progression since a PDGFRB downregulation impairs immediately GBM progression (A.C.V.-B." (PMID 34316686, 2020). "A possible mechanistic explanation of the elevated angiogenic response would attribute ablation of vascular pericytes by PDGFRβ inhibition, allowing further exposure of tumor vessels to FGF-2 and VEGF, and consequently leading to excessive sprouting of microvessels." (PMID 32709869, 2020). "Notably, small molecules inhibitors of PDGFRβ have been reported to augment tumor immunity by depletion of FoxP3-expressing Tregs and increase in CD8+ T cells in humans and advanced tumor-bearing mice." (PMID 32892748, 2020). "Importantly, we show that the PDGFRβ aptamer augments antitumor immunity and potentiates anti-PD-L1 antibody inhibitory effects on tumor growth and lung metastases formation in 4 T1 TNBC orthotopic mouse model." (PMID 32892748, 2020). "Given that FAK plays a role in cell migration and adhesion, it was not necessarily surprising that pericyte FAK deficiency reduced significantly the association of NG2-positive and α-SMA-positive (that were also shown to be Pdgfrβ-positive) pericytes with tumour blood vessels." (PMID 32499572, 2020). "Also, we showed that the aptamer is able to transcytose the blood-brain barrier (BBB), by binding to PDGFRβ highly expressed on endothelial cells of vessels that vascularize the tumor." (PMID 32892748, 2020). "We investigated the expression of human PDGFRα because it is recognized as marker of tumor RMS cells, while the variant β (human PDGFRβ) was primarily detected in vascular stroma and it has been shown to be more related to wound healing and leukocyte differentiation." (PMID 33585217, 2020).
tumor (continued). "We found that target molecules of these inhibitors, including VEGFR1, VEGFR2, VEGFR3, VEGFA and PDGFRB, were markedly expressed only in cancer 1 and 2 clusters (primary tumor and LN metastasis), while their expressions in cancer 4 (bone metastasis) and CSC clusters were relatively low." (PMID 33162821, 2020). "In addition, α-SMA-negative and PDGFRβ-positive CAF subpopulations contribute to the malignant potential of tumor cells by interacting with integrin α11." (PMID 32546182, 2020). "We found that tumor-associated pericytes marked by co-expression of fibroblast activation protein α (FAP) and PDGFRβ represent major stromal cell subsets in both human GBM and mouse GBM models, while a fraction of mesenchymal neoplastic cells also express FAP in patient tumors." (PMID 33308315, 2020). "Activation of PPARβ in blood vessels promotes tumor vascularization and the progression of different cancer cell types through direct activation of platelet-derived growth factor receptor beta (PDGFRβ), platelet-derived growth factor subunit B (PDGFB), and the c-Kit." (PMID 32028670, 2020). "As 92.1UM promotes retinal pericyte-CAF transition of HRPC mediated by PDGF-B, leading to a putative immune-modulatory function as well as tumor progression capacity, phospho- and total PDGFRβ protein levels were analyzed in order to validate the involvement of PDGR-BB activity in our model." (PMID 32756477, 2020). "However, the tumor accumulations of the radiolabeled probes were low, which suggests the requirement of other potential PDGFRβ-targeted radiopharmaceuticals." (PMID 33374773, 2020). "Thus, selective inhibition of host PDGFRβ in ASKA mice by 1-NaPP1 significantly inhibited tumor growth in LLC and B16/PDGF-BB tumor models that express high levels of PDGF-BB." (PMID 31938055, 2020). "However, treatment with imatinib- or a PDGFR-blocking antibody inhibited pericyte recruitment by suppressing PDGFRβ signaling, subsequently reducing tumor growth in ES cells in vivo." (PMID 32754598, 2020). "Our data suggest that targeting PDGFRβ in the tumor stroma could have therapeutic value in patients with high tumor PDGF-BB expression." (PMID 31938055, 2020). "Unexpectedly, anti-PDGFRβ alone treatment augmented tumor angiogenesis in FGF-2+ tumors." (PMID 32709869, 2020). "We found that specific inhibition of PDGFRβ activity strongly reduced tumor growth and angiogenesis in tumors with high PDGF-BB expression, while the less specific kinase inhibitor imatinib rendered negligible suppression of tumor growth even though it affected the vascularization of tumors." (PMID 31938055, 2020). "However, other studies, in different cancer models, have demonstrated that pericyte depletion through interference with PDGFRβ signaling can favor tumor growth." (PMID 31308421, 2019). "In addition, a strong upregulation of PDGFRα and PDGFRβ was detected in hSCC11 PD/S cells, indicating that tumor cells from human advanced SCCs induce PDGFR signaling." (PMID 30874597, 2019). "The PDGFRβ was mainly expressed in glomerulus in the tumor adjacent tissues." (PMID 31690270, 2019). "The ratio of PDGFRA to PDGFRB expression in primary tumors may be predictive of tumor response to TMZ." (PMID 31336733, 2019). "As expected the addition of PDGFRβ inhibitor Nilotinib with MEK1/2-JAK2 inhibition in triple combination therapy significantly suppressed the tumor growth compared to the MEK1/2-JAK2 double combination therapy due to induction of apoptosis, as evident by Apoptag staining." (PMID 30777101, 2019). "In vitro studies identified PDGFRβ as a direct substrate for LOXL2, and indicated that LOXL2 and PDGF-AB together secreted by tumor cells optimally activated PDGFRβ in fibroblasts to promote proliferation and the tendency toward fibrosis via ERK activation, but not AKT." (PMID 31086173, 2019).
tumor (continued). "Complex interactions between tumor cells and their microenvironment, including the development of a rich vascular blood supply, are required for metastasis and given its location, our results suggest PDGFRβ is involved in these interactions in WT." (PMID 31565187, 2019). "However, a PDGFRβ specific neutralizing antibody almost completely ablated the pericytes from tumor tissues, indicating that the PDGFRβ receptor signaling is involved in FGF-2-induced pericyte recruitment." (PMID 29423271, 2018). "The cell-by-cell analysis and mixture modeling suggests that this ensemble average does not capture the subpopulations having high-PDGFR plasma membrane localization: 66 and 16% of mouse tumor EC-like cell membrane had ~23,400 PDGFRα and ~19,800 PDGFRβ, respectively." (PMID 30050899, 2018). "Moreover, the excess amount of PDGFRβ ligand can reduce [77Br]2 uptake in PDGFRβ-positive tumor cells and in the in vivo blocking experiments using tumor-bearing mice." (PMID 29991770, 2018). "Both of these actions are driven by PDGF-BB—PDGFRβ signalling, implying that tumour growth may be limited by agents blocking this signalling, such as imatinib and sunitinib (although these drugs also block other tyrosine kinases)." (PMID 30097696, 2018). "In agreement with findings in GBM, by performing an immunohistochemical analysis in a cohort of 200 human TNBC samples, we found that the tumor cell expression of PDGFRβ marks a restricted subgroup of tumors (5.5% of total cases) with invasive and mesenchymal/stem-like phenotype." (PMID 30428522, 2018). "Moreover, pretreatment with VEGFR and PDGFRβ inhibitors can inhibit tumor growth in a mouse colorectal carcinomatosis model." (PMID 29152075, 2017). "Indeed, by IHC staining, we detected a statistically significant increase in staining of the tumour stroma compared to the normal stroma for PDGFRβ, indicating an increase in PDGFRβ protein in CAS." (PMID 28531107, 2017). "Pharmacological or genetic ablation of PDGFRβ+ vascular pericytes at early stages of cancer development reduced lung metastases, whereas increased metastases were observed when pericytes were depleted at later stages in tumor development." (PMID 28878242, 2017). "Since polymerization might improve the stability and avidity of the affibody, in this study, we first prepared the dimeric ZPDGFRβ affibody and determined its PDGFRβ-dependent pericyte-binding and tumor-homing capabilities in mice bearing tumor grafts." (PMID 29182023, 2017). "Consequently, pericytes are major PDGFRβ+ mural cells in tumor grafts, thus conjugation to the ZPDGFRβ affibody would deliver PS to pericytes." (PMID 29182023, 2017). "However, although many NG2-, PDGFRβ-, or αSMA-positive pericytes are recruited to the tumor clump in WT mice, the number of pericytes and the tumor volume are significantly reduced in Flt-1 TK−/− mice, which display an impairment of macrophage function." (PMID 28634350, 2017). "Since PDGFRβ and αSMA are also expressed in pericytes their increased expression during tumor progression may, in part, reflect tumor-induced angiogenesis." (PMID 27128408, 2016). "Given the close proximity of PDGFRβ-positive cells to carcinoma cells we wished to determine whether carcinoma cells in the invasive tumor fronts also express PDGFRβ." (PMID 27128408, 2016). "Among the other two hub genes both with high degree of 16, EGFR has been among the most important prognostic factors for HNSCC, while the kinase PDGFRB was found to be up regulated in tumor indicating the effectiveness of tyrosine and serine-threonine kinase inhibitors in the treatment of HNSCCs." (PMID 26064958, 2015). "This suggests that levels of urinary PDGFRB increase with tumor size." (PMID 24801713, 2014). "In regard to molecular imaging, non-invasive PDGFRβ visualization in solid tumors is important since it could optimize treatment monitoring, allowing a detailed evaluation of tumor response to therapeutic modalities." (PMID 22791264, 2013).